AGO2 (argonaute RISC catalytic component 2)
Diseases named in the same sentence as AGO2 in open-access papers (continued):
Sharing a sentence is not in itself a finding about the gene and the disease.
ovarian carcinoma (9 papers, 2014 to 2025). A malignant neoplasm originating from the surface ovarian epithelium. "Higher expression levels of AGO1 and AGO2 associated with tumor progression have been found in different cancer entities, such as in epithelial skin cancer and ovarian cancer." (PMID 29857476, 2018). "Knockdown of Ago2, the primary mediator of RNAi, rescued the toxicity in an ovarian cancer cell line." (PMID 37059938, 2023). "All these results showed that the amount of CACNA1G-AS1 and FTH1 pulled down by the AGO2 antibody significantly increased in ovarian cancer cells transfected with IGF2BP1." (PMID 37304234, 2023). "In this section, we overexpressed IGF2BP1 in ovarian cancer cells and coimmunoprecipitated target RNA with an anti-AGO2 antibody." (PMID 37304234, 2023). "We found a limited number of SNPs in our searches, however further work will be required to determine what effects these specific SNPs have on the regulation or function of Ago2, as some SNPs have previously been shown to exert effects in ovarian cancer." (PMID 31324173, 2019). "In their study, higher Ago2 protein expression in ovarian cancer before chemotherapy correlated with shorter progression free survival." (PMID 25295252, 2014). "The study group saw similar trends for both Ago1 and Ago2 with respect to overall survival, suggesting a pivotal role of these molecules in ovarian cancer progression." (PMID 25295252, 2014). "We observed that knockdown of Ago2 rescued CD95L mRNA toxicity in an ovarian cancer cell line." (PMID 37059938, 2023). "Moreover, using Ago2‐RIP assay, we showed that immunoprecipitation with Ago2 antibody greatly pulled down both circATRNL1 and miR‐378 in ovarian cancer cells compared with immunoprecipitation with normal IgG antibody." (PMID 33372356, 2021).
Obesity (8 papers, 2018 to 2025). Accumulation of substantial excess body fat. "AGO2 emerged as a central player that is implicated in both obesity and in weight loss and which shows the highest number (n = 15) of interactions." (PMID 34716428, 2022). "AGO2 emerged as a central regulatory molecule in the network containing miRNAs implicated in both obesity and weight loss." (PMID 34716428, 2022). "Functionally, Ago2 is expressed in a number of tissues including the liver and pancreas, and is critical for the obesity‐associated pathophysiology." (PMID 36062491, 2022). "The regulation of energy metabolism by Ago2 provides a novel paradigm in which RNA silencing plays an integral role in determining basal metabolic activity in obesity-associated sequelae." (PMID 30201950, 2018). "In support of these observations, there was an increased copy number of mitochondrial-DNA (mtDNA) in the Ago2-deficient liver in obesity." (PMID 30201950, 2018). "This study demonstrates that hepatic Ago2-mediated RNA silencing regulates energy expenditure during the course of obesity and its inactivation protects from obesity-associated glucose intolerance and hepatic steatosis in mice." (PMID 30201950, 2018). "Changes in hepatic Ago2-mediated energy balance between energy production and consumption in response to nutrient challenges appears to contribute to the pathogenesis of obesity-associated sequelae." (PMID 30201950, 2018). "We find that HFD‐induced obesity is defined by the metabolic dysregulation and disrupted energy homeostasis, and that these changes are largely associated with the evaluated expression of Ago2 in different adipose depots." (PMID 36062491, 2022). "Interestingly, Ago2 expression is associated with obesity and an increased amount of adipose tissue." (PMID 36062491, 2022). "Importantly, AGO2 inactivation protects from obesity-associated glucose intolerance and hepatic steatosis in mice." (PMID 32503341, 2020). "In agreement with the activation of AMPK, other AMPK substrates, UNC-51-like kinase 1 (ULK1), and Mitochondrial fission factor (MFF) are increased in the liver of L-Ago2 KO mice, suggesting enhanced autophagy/mitophagy and improved mitochondrial quality in the Ago2-deficient liver in obesity." (PMID 30201950, 2018). "Although PPARα did not feature as a key molecule in our pathway analyses, recent studies carried out in the liver suggest that Ago2 function is intrinsically associated with PPARα and, consequently, with mitochondrial energy metabolism that may contribute to obesity-associated pathophysiology." (PMID 34716428, 2022). "Inhibitors which target Slc13a1 and agonists which target Nr1i2 or Ago2 are predicted to have a similar BL6-specific protective effect against diet-induced obesity." (PMID 37871105, 2023). "Recent studies have revealed that Ago2‐miRNA‐mediated mRNA regulation plays a significant role in the hepatic and adipose energy metabolism of obesity." (PMID 36062491, 2022). "Here, we show that Ago2 expression is increased in adipose tissue of mice with food‐induced obesity." (PMID 36062491, 2022). "Notably, Ago2 is also abundant in the liver cells plays a crucial role in the regulation of glucose homeostasis in severe obesity; Ago2‐deficiency in the liver could protect against severe obesity‐induced insulin resistance and diabetes via Ago2‐PPARα signaling pathway." (PMID 36062491, 2022). "It will be important to further investigate mechanism of how Ago2 and related miRNAs in the progression of diet‐induced obesity." (PMID 36062491, 2022). "Mechanistically, our measurements further show HFD induced obesity resulted in an alteration in expressions of Ago2‐mediated miRNA signaling in adipose tissues." (PMID 36062491, 2022). "For example, in pancreatic β cells, the expression of Ago2 is significantly increased in the ob/ob islets and shows beneficial impacts on obesity and insulin resistance by promoting pancreatic β cell expansion." (PMID 36062491, 2022).
Obesity (continued). "This study identifies that the Ago2‐miR‐148a signaling pathway plays a key role in the progression of diet‐induced obesity." (PMID 36062491, 2022). "Several studies have shown that tissue‐specific Ago2 and its mediated miRNA signaling pathways play a crucial role on body metabolism and contribute to the progression of obesity." (PMID 36062491, 2022). "Obesity induces the increase of Ago2 expression, which enhances the silencing effect of miR‐148a on AMPKα, and subsequently reduces the activity of AMPKα, inhibits the calorie burning ability of adipocytes, and finally leads to lipid accumulation." (PMID 36062491, 2022). "In conclusion, our observations on the Ago2 provide further insight into identifying a specific miRNA signaling which regulate obesity and energy homeostasis in adipose tissue." (PMID 36062491, 2022). "Now, our study further provides evidence that Ago2 is expressed in adipose tissues and it's expression is increased in diet‐induced model of obesity, in consistent with the role of Ago2 in obesity." (PMID 36062491, 2022). "Together, those results demonstrate Ago2 as an important regulator in physiological processes of adipose tissues and further reinforce the role of Ago2‐mediated miRNA signaling in regulation of HFD‐induced obesity." (PMID 36062491, 2022). "Here, we report that hepatic Argonaute 2 (Ago2)-mediated RNA silencing regulates both intrinsic energy production and consumption and disturbs energy metabolism in the pathogenesis of obesity." (PMID 30201950, 2018). "Taken together, these data indicate that inactivation of Ago2, but not Ago1, in the liver increases mitochondrial capacity and energy expenditure, which appears to link to improvement of obesity-associated pathophysiology." (PMID 30201950, 2018). "In conclusion, our results highlight that Ago2 uniquely regulates energy production and consumption in the liver, and suggest hepatic Ago2-mediated RNA silencing is a key regulator of glucose and lipid metabolism during the pathogenesis of obesity." (PMID 30201950, 2018). "Furthermore, obesity significantly increases the expression of Ago2 in islets, giving rise to pancreatic β‐cell proliferation and insulin resistance, which further provide evidence for Ago2 in the regulation of cellular metabolism." (PMID 36062491, 2022). "This Ago2-mediated RNA silencing is a critical mechanism that connects the dots between protein translation, energy production and consumption, and AMPK activity—disruption of such events is a well-recognized feature in obesity and the pathogenesis of obesity-associated sequelae." (PMID 30201950, 2018).
bladder cancer (7 papers, 2016 to 2023). "In order to assess the clinical relevance of AGO1, AGO2 and Drosha as prognostic markers in bladder cancer patients, the Kaplan–Meier analyses of dichotomized immunoreactivity data were conducted." (PMID 29857476, 2018). "The association of AGO1 with AGO2 and Drosha according to our McNemar test hints at similar processes and changes of miRNA machinery in bladder cancer, although AGO2 and Drosha were different." (PMID 29857476, 2018). "It was found that miR-1 decreased the expression of UCA1 in bladder cancer cells in an Ago2-slicer-dependent manner." (PMID 26949706, 2016). "As expected, knockdown of AGO2 led to a profound reduction in cell proliferation in a mutant HRASG12V/G12V-driven urinary bladder carcinoma cell line (T24) and a HRASG13V/WT-driven acute lymphocytic leukemia cell line (Kasumi-2) compared to a matched nontargeting control shRNA." (PMID 35923912, 2022). "Furthermore, after the transfection of pre-miR-1 or following the treatment of UCA1 shRNA, cell proliferation and motility decreased in bladder cancer cell lines in an AGO2-mediated manner." (PMID 31694571, 2019). "In our study, the altered expressions of AGO1, AGO2, and Drosha were investigated immunohistochemically in bladder cancer to evaluate their diagnostic and prognostic potential in non-invasive and invasive bladder carcinoma." (PMID 29857476, 2018). "In addition, Ago2-related RIP assays revealed that circKIF4A, NOTCH2 and miR-375/1231 were enriched for Ago2 in RT-112 and BIU-87 bladder cancer cells." (PMID 32457613, 2020). "With regard to bladder carcinoma, previous studies have described the overexpression of Drosha, AGO1 and AGO2 compared to non-malignant bladder tissue, which we could attribute to NMIBC." (PMID 29857476, 2018).
malaria (7 papers, 2016 to 2021). Malaria is a serious and sometimes fatal disease caused by a parasite that commonly infects a certain type of mosquito which feeds on humans. "The reported localisation of Ago2 in early ring stage parasites and the observed phenotype upon Ago2 over-expression prompted us to investigate if indeed host Ago2 function had also been co-opted by the malaria parasite." (PMID 33501380, 2020). "To directly investigate whether host Ago2 plays a role in blood stage malaria parasites, we tested the effect of an Ago2 inhibitor againstP." (PMID 33501380, 2020). "Whether ptRFs function by binding to host AGO2 or other small RNA biogenesis-related apparatus should be further explored to strengthen our understanding of the interaction between malaria parasites and their human host." (PMID 30646930, 2019). "A similar outcome has been documented in the case of the African malaria mosquito, Anopheles gambiae, where dsRNA-mediated silencing of AGO2, which functions in conjunction with DCR2 in this mosquito, resulted in increased O’nyong-nyong virus (ONNV) viral loads." (PMID 30470195, 2018). "In summary, we conclude that there is no Ago2-mediated miRNA activity in malaria parasites, despite a previous report suggesting otherwise." (PMID 33501380, 2020). "For instance, studies have shown that the Ago2-miR-451 complex derived from infected RBCs is taken up by endothelial cells and can alter vascular function through RBC extracellular vesicles in malaria, even though RBCs lack the target mRNAs of miRNAs inside the cells." (PMID 30154732, 2018).
ZIKV infection (7 papers, 2021 to 2025). "In cells that were not infected with BinJV or BinJ-ZIKV, ZIKV grew to similar titers in both cell types (1.4 × 108 TCID50/ml and 1.5 × 108 TCID50/ml at 4 days post ZIKV infection for Aag2 and Ago2-deficient Aag2, respectively)." (PMID 39845567, 2025). "To determine the correlation between the RNAi and insulin pathways during ZIKV infection, we used gene-specific primers to estimate Dicer-2 and Ago-2 expression in insulin mutants." (PMID 35844546, 2022). "As knockdown and knockout of Ago2 normally results in increased virus replication, this would be specific for ZIKV infection." (PMID 34205194, 2021). "To test whether insulin signaling confers RNAi resistance to ZIKV infection in Drosophila hosts, we estimated the transcript levels of Dicer-2 and Ago-2 in foxo and chico null mutants." (PMID 35844546, 2022). "To further investigate whether the observed high SIE and CPE in C6/36 cells upon BinJV or BinJ-ZIKV infection was due to the lack of a functional RNAi response, we generated Argonaute2 (Ago2) deficient Aag2 cells using CRISPR/Cas9 technology." (PMID 39845567, 2025). "In contrast, ZIKV infection was not negatively affected in Ago2 knock-out cells during DENV-1 co-infections." (PMID 37440582, 2023). "Although vsiRNA transgenic mosquitoes can effectively block virus transmission, downregulation of Dicer2 and Ago2 did not enhance ZIKV infection in mosquitoes." (PMID 34061577, 2021). "In terms of the involvement of Wolbachia in altering the immune signaling in D. melanogaster challenged with Zika virus, we find that the presence of the endosymbionts in female or male adult flies fails to modify the expression of Dicer-2 and Ago-2 genes upon Zika virus infection." (PMID 38903791, 2024). "Interestingly, CHIKV negatively affected ZIKV infection during co-infections in case of Ago2 knock outs, but not AF5 cells." (PMID 37440582, 2023). "In addition, the depletion of the RNAi pathway genes Dicer 2 and Ago2 also did not enhance ZIKV infection." (PMID 34061577, 2021).
arbovirus infection (6 papers, 2015 to 2025). A viral infection that is transmitted by an arthropod. "Taken together, our studies reveal novel roles for Ago2 in protecting mosquitoes from arbovirus infection and associated death." (PMID 37723154, 2023). "Alongside a recently developed and characterized Ago2 knockout cell line and exo-siRNA pathway associated proteins, this toolset now allows in-depth investigations of the exo-siRNA pathway during arbovirus infection in mosquito cells." (PMID 34990484, 2022). "Here we show that the Ae. aegypti Ago2 is essential for controlling arbovirus infection, and thereby an important regulator of mosquito disease transmission." (PMID 37723154, 2023). "Our study shows a fundamental role for Ago2 and the siRNA pathway in controlling arbovirus infection in mosquitoes, as well as in protecting the mosquitoes against mortality upon arboviral infection by modulating DNA repair, apoptosis, and autophagy." (PMID 37723154, 2023). "To demonstrate the essential function of Ago2 in the Ae. aegypti siRNA pathway, we used CRISPR/Cas9 to knock out Ago2 and then investigated its role in defending against arbovirus infection." (PMID 37723154, 2023). "Taken together, these results demonstrate that Ago2 disruption severely impairs the induction of autophagy upon arbovirus infection." (PMID 37723154, 2023). "Midguts of Ago2−/− females displayed a different infection pattern upon arbovirus infection: for MAYV at 4 dpi, the infection of the control midgut was restricted to specific areas, whereas half the Ago2−/− midgut was heavily infected." (PMID 37723154, 2023). "To determine whether the effect of Ago2 disruption on arbovirus infection was the result of a defective siRNA pathway, we performed small RNA (sRNA) sequencing of Ago2−/− mutants and WT mosquitoes after MAYV infection." (PMID 37723154, 2023). "Therefore, to study the role of the siRNA pathway in controlling arbovirus infection in mosquitoes, we have now generated siRNA pathway-defective mosquitoes by knocking out Ago2 in Ae. aegypti." (PMID 37723154, 2023). "Do the vsiRNAs in Ago2-RISCs turn over during the course of an arbovirus infection?" (PMID 25690800, 2015). "Hence, a mutation in the Piwi_ago-like domain had the strongest impact on arbovirus infection and Ago2 endonuclease activity, which was also shown in dsRNA-mediated silencing of endogenous genes, and the Ago2−/− line was therefore used as a Ago2 mutant line for the subsequent experiments." (PMID 37723154, 2023).
breast tumor (6 papers, 2014 to 2024). "We then used an orthotopic breast tumor model to investigate the role of Ago2/CAV1 interaction in tumor formation and metastasis." (PMID 38649663, 2024). "Further, corresponding to the increased Ago2/CAV1 interaction in metastatic breast tumors, we observed that the levels of EV miR-3613-3p in circulation increase with tumor progression into metastasis." (PMID 38649663, 2024). "Together with our clinical findings on AGO2 expression and the luminal B subtype, we suggest that AGO2 is a regulator of altered ERα signaling in breast tumors." (PMID 29657266, 2016). "Even though miR-21 is highly expressed both in MCF7 cells and patient breast tumor samples, we were only able to identify a small number of its targets crosslinked by AGO2-PAR-CLIP." (PMID 24398324, 2014). "AGO2 expression correlates with a poor clinical outcome in ERα+ breast tumor samples." (PMID 29657266, 2016). "Here, we demonstrate for the first time, high AGO2 expression levels in a subset of ERα+ breast tumors (luminal B and ERα+/PGR−), similar to AGO2 expression observed in ERα− tumors." (PMID 29657266, 2016). "We found that these genes were deregulated in ER+ compared to ER− breast tumors: DICER1, DROSHA and DGCR8 were significantly under-expressed in ER− while AGO2 was moderate over-expressed in ER−." (PMID 26141719, 2015). "In addition, we show that a subset of ERα+ breast tumor samples, characterized as luminal B and ERα+/PGR−, demonstrated high AGO2 levels, similar to those observed in the ERα− tumor types." (PMID 29657266, 2016). "Interestingly, tumor samples with a breast tumor type categorized as luminal B and an ERα+/PGR− receptor status demonstrated high AGO2 expression levels compared to samples with luminal A/ERα+/PGR+ receptor status." (PMID 29657266, 2016). "Furthermore, Kaplan–Meier analysis of AGO2 expression correlated with a poor prognosis for recurrence free survival in ERα+ breast tumors but not in ERα− tumor samples." (PMID 29657266, 2016).
diabetes (6 papers, 2015 to 2025). "It is noteworthy that in this Ago2 IP-seq experiment, we observed several miRNAs which have been confirmed to be associated with diabetes or metabolic abnormalities, such as miR-30b, miR-143, and miR-27b." (PMID 32938376, 2020). "Diabetes-induced reductions in SIRT3 levels in cardiomyocytes lead to increased malonylation of cytoplasmic Ago2, impairing its interaction with Timm17b." (PMID 40861070, 2025). "The present study shows that Ago2 is highly expressed in the neurovascular part of cavernous tissue and is significantly decreased under pathological conditions, such as diabetes." (PMID 36769259, 2023). "We used a diabetes-induced ED mouse model to evaluate the angiogenic effect of Ago2 and its optimal therapeutic dose within in vivo studies." (PMID 36769259, 2023).